IRF3 (interferon regulatory factor 3)
Diseases named in the same sentence as IRF3 in open-access papers (continued):
Sharing a sentence is not in itself a finding about the gene and the disease.
infection (continued). "In addition, phosphorylation of TBK1 (pTBK1) and IRF3 (pIRF3) was observed in both the PRRSV-infected cell group and poly (I: C)-stimulated cell group at 12 h and 24 h post-infection." (PMID 41012704, 2025). "Consistently, we found that IRF7 mRNA expression, but not IRF3 mRNA, was induced after 6 h of infection and was reduced by M3, further confirming that IRF7 activation is regulated by IFN." (PMID 39601535, 2025). "Early after infection, viral RNA is sensed by RIG-I and MDA5, leading to phosphorylation and the nuclear translocation of IRF3/7; this step is captured efficiently by the ISRE-luciferase reporter, which lacks chromatin restraints and is transcribed as soon as activated IRFs bind its promoter." (PMID 40732740, 2025). "To further validate these findings, we knocked down Usp8 in Usp8fl/fl mouse embryonic fibroblast (MEF) cells via infection with Cre lentivirus and found that the EMCV‐induced expression of Ifnb1 and Cxcl10 and the EMCV‐induced phosphorylation of TBK1 and IRF3 were significantly impaired." (PMID 40525588, 2025). "The translocation of IRF-3 is accompanied by an elevation in the phosphorylation of serine and threonine residues, and its interaction with the CREB co-activator only occurs following infection." (PMID 41202012, 2025). "Notably, TLR signaling genes interferon regulatory factor 1 (IRF1) and MyD88 are significantly induced by MVA infection in DSK cells, probably to counterbalance the reduced IFN-I response of the cytosolic DNA-sensing cGAS/STING/IRF3 axis." (PMID 40981440, 2025). "Upon infection with SeV, the phosphorylation of IRF3 was observed when IRF3 was over-expressed in the absence of filovirus proteins." (PMID 40872796, 2025). "Furthermore, the HSV-1 virus, a DNA virus discussed earlier, induces mitochondrial damage and release of mitochondrial DNA (mtDNA) upon infection, triggering both the cGAS/STING/IRF3 and RIG-I-MAVS signaling pathways." (PMID 40016186, 2025). "Moreover, AF-9 strain infection or poly (I: C) stimulation led to upregulation of the production of RIG-I, MDA5, MAVS, TRAF3, and TBK1 and phosphorylation of TBK1 and IRF3 in PAMs." (PMID 41012704, 2025). "Finally, we observed unhindered p-IRF3 translocation in the HCMVGFP+ cells compared with the HCMVGFP− cells, suggesting that during productive infection, the host cells can overcome the HCMV control of p-IRF3 and viral immune evasion." (PMID 40872823, 2025). "During normal infection, gcDDX56 binds to gcKPNB3, “locking” its function into cytoplasmic IRF3 degradation (rather than nuclear transport)." (PMID 41217109, 2025). "To assess the role of poxin on IRF3 activation during VACV infection, we engineered a recombinant VACV lacking B2R (VACV.ΔB2)." (PMID 39431915, 2024). "Upon infection by RNA or DNA viruses, activated TBK1 and IKKε/i phosphorylate IRF3 at specific serine residues; and IRF3 then undergoes nuclear translocation to initiate the transcription of type I IFN by binding to specific regulatory elements known as IFN-stimulated response elements (ISREs)." (PMID 38396775, 2024). "In the context of poultry, miR-27b is upregulated during infection with Infectious Bursal disease virus (IBDV) and suppresses viral replication, upregulating the expression of ISGs like interferon beta (IFN-β), interferon regulatory factor 3 (IRF-3), and nuclear factor kappa beta (NF-κβ)." (PMID 39599862, 2024). "During infection, STING activates IRF3 which interacts with BAX." (PMID 38459007, 2024). "For this purpose, we analyzed the phosphorylation status of several of the main proteins of this pathway (STING, IRF3, and TBK1) at different post-infection times (4, 8, and 16 hpi) during infection with the recombinant virus compared to the parental Arm/07/CBM/c2 virus." (PMID 38675789, 2024).
infection (continued). "Infection of wild type (WT) A549 cells with Sendai virus (SeV) or Zika virus (ZIKV) resulted in robust IFN-I (IFNB1) and IFN-III (IFNL1) transcription and activation of both IRF3-dependent (ISG54) and NF-κB-dependent (NFKBIA) genes." (PMID 38001254, 2024). "Infection with VSV or H1N1 enhanced the interaction between FXR and IRF3." (PMID 39220861, 2024). "Interestingly, infection of macrophages resulted in low but reproducible STING and IRF3 activation even when D5 expression was abolished." (PMID 39431915, 2024). "Furthermore, to identify IRF3-mediated apoptosis is Puma-dependent, Puma−/− cell lines were transfected with IRF3 or PBLD, and western blotting analysis was conducted to assess their ability to induce apoptosis during BPIV3 infection." (PMID 39362857, 2024). "Another study investigating the RNA virus Sendai virus showed that IFITM3 does not limit infection and actually promotes the autophagic degradation of IRF3, limiting type I interferon responses." (PMID 39772131, 2024). "In summary, this report shows that the infection with two different OPXV species (ECTV and VACV) has the capacity to induce STING and IRF3 activation in at least two different cell types and that this is mediated by released as well as replicated viral genomes." (PMID 39431915, 2024). "The results of RT-qPCR demonstrated that, unlike wild-type IRF3, both individual mutations impaired Ifnβ and ISGs induction in the absence of PBLD during BPIV3 infection." (PMID 39362857, 2024). "In contrast to IRF3-driven expression, transcription of the NF-κB-dependent genes Nfkbia and Tgfb1 was not affected by the presence or absence of M35 during infection." (PMID 37289084, 2023). "Next, we used herpes simplex virus 1 (HSV-1) strain 17, which we found not to activate IRF3 during HFF infection, but that did rapidly degrade DNA-PKcs, as previously reported in other cell lines." (PMID 38269102, 2023). "IRF3 locates in the cytoplasm in the unstimulated state and is phosphorylated at specific serine residues which allow its dimerization and nuclear translocation to initiate IFN-I signaling upon infection." (PMID 37366613, 2023). "Furthermore, the temporal expression profiles of eight selected antiviral-related mRNA including IRF3, IRF7, IKKβ, TBK1, IFIT1, IFI44, MX1 and ISG15 were detected by qRT-PCR, which showed a significantly stronger response at early infection under 20 °C." (PMID 37627029, 2023). "In addition, IRF-3 and IRF-5 expression was significantly (p < 0.05) higher in cells treated pre-infection than in post-infection experiments." (PMID 37317211, 2023). "IRF7 induction has been noted in SNV infection of HLMVECs and during infection of Syrian golden hamsters where there was a similar lack of IRF3 induction with upregulation of IRF7." (PMID 37766212, 2023). "This increase in IFNβ expression could be explained by the observed infection-induced increases in the expression of MAVS and IRF3, which were reported to be involved in IFNβ production." (PMID 36754974, 2023). "Similar to the NCP-BVDV virus, CP-BVDV (NADL strain) does not induce interferon response after infection and blocks interferon-stimulating genes induced by paramyxovirus infection, resulting in a significant decrease in IRF3 expression." (PMID 37090696, 2023). "We found that while SeV strongly induced IRF3 translocation, in contrast, infection with either WT or ΔORF6 SARS-CoV-2 virus did not induce IRF3 activation at this early time point 24 hpi." (PMID 37377442, 2023). "This may indicate that the antiviral response induced by C. sorokiniana is mediated by RIG-I, IRF-3, and IFN-α in pre-infection experiments." (PMID 37317211, 2023). "DNA-PK has been reported to act in STING-dependent and -independent pathways depending on the cell type and activation context, and to activate IRF3 but not NF-κB-dependent signaling during infection or stimulation." (PMID 38269102, 2023). "IRF3 and IRF7 were also activated from 2 to 5 days after OC43 infection." (PMID 37197656, 2023).
infection (continued). "We conclude that IFNA1, IRF3, CXCL8, CXCL10, IFNB1, and CHUK are the key hub genes involved in the H5N1 human infection, which makes a major contribution towards the inflammation or cytokine storm leading to the prognosis of the disease and critical clinical outcomes." (PMID 37515084, 2023). "Our data indicated that IRF3 agonist reduced neuronal damage in the brains and spinal cords and alleviated muscle and lung pathologies, while TBK1 inhibitor exacerbated pathological changes after infection." (PMID 36626364, 2023). "Infection of Calu-3 cells with SARS-CoV-2 did not prevent IRF3 phosphorylation, nor STAT1 or P65 translocation as it did with infections with SARS-CoV-2." (PMID 37526812, 2023). "Surprisingly, similar to WT mice Irf3−/− and Irf7−/− animals survived the infection with no obvious signs of disease." (PMID 37737190, 2023). "It is worth noting that IDH1(R132H) downregulated the total protein levels of IRF3/7 in cells either with or without VSVΔ51 infection." (PMID 37880243, 2023). "In addition, IFN-α, IRF-3, and RIG-I relative expression was significantly (p < 0.05) higher in pre-infection experiments than in post-infection ones." (PMID 37317211, 2023). "Unlike strain 17, dl1043 infection of HFFs did not result in a reduction of DNA-PKcs expression but did result in measurable IRF3 activation." (PMID 38269102, 2023). "At 2 h post-infection, we did not observe changes in the nuclear accumulation of IRF3, as compared to control macrophages or to macrophages treated with the synthetic double-stranded RNA Poly:IC." (PMID 35154115, 2022). "Induction of the IFN I pathway after infection with the wt isolate was evident by up-regulation of several interferon-induced proteins, i.e., IFIT-I, ISG15, IFI44, GIG1, interferon-induced very large GTPase 1, IRF3, IRF7, and Mx." (PMID 35215144, 2022). "Here, we describe DDX50, which shares 55.6% amino acid identity with DDX21, as a non-redundant factor that promotes activation of the IRF3 signalling pathway following its stimulation with viral RNA or infection with RNA and DNA viruses." (PMID 35215908, 2022). "Consistent with the imaging data, we did not detect an increase in IRF3 phosphorylation following infection." (PMID 35022513, 2022). "Moreover, knockdown of UL13 in MEFs also enhanced phosphorylation of TBK1, IKKε, and IRF3, the downstream components of STING, and stabilized the protein levels of STING at 6 and 12 h post-infection of PRV." (PMID 35584187, 2022). "Infection of macrophages derived from IRF3-KO mice with L. monocytogenes failed to induce NOS2 expression observed in W.T. macrophages." (PMID 36010574, 2022). "During early infection, attenuated NH/P68 activates the c GAS-STING-IRF3 cascade, which induces STING phosphorylation and translocation through the c GAMP mechanism to activate TBK1 and IRF3 and produces high levels of β-interferon (IFN-β)." (PMID 36013434, 2022). "We found that the mRNA expression level of IRF7 was significantly increased at 18 and 24 h after SVA infection (P < 0.05), but the mRNA expression level of IRF3 was not significantly increased (P > 0.05)." (PMID 35308346, 2022). "Activation of the cytosolic DNA sensing pathway following R. equi infection leads to phosphorylation of IRF3 and initiation of a type I IFN response within 4h of infection, while intracellular bacteria are still replicating within the R. equi-containing vacuole." (PMID 34473814, 2021). "In particular, TLR3 might act via IRF3-producing IFN-α and IFN-β during the first 24 h post-infection." (PMID 34576716, 2021). "The results show a dramatic reduction of IRF3 starting at 24 h post-infection, with non-detectable levels at low MOI at 48 h post-infection." (PMID 33372854, 2021). "In the absence of IRF3-mediated gene transcription, the Irf3S1/S1 mice were protected from lethal infection with SeV, demonstrating the importance of RIPA in protection from respiratory viral pathogenesis." (PMID 33805458, 2021).
infection (continued). "Upon infection with RNA viruses, TBK1 is activated by the upstream protein MAVS, and activated TBK1 recruits IRF3 and IRF7; these proteins undergo TBK1-mediated C-terminal phosphorylation to trigger their dimerization and nuclear translocation, an event followed by induction of IFN secretion." (PMID 34782737, 2021). "As such, the ubiquitination of IRF3 that targets the protein for destruction is a negative regulatory mechanism by which the body returns to homeostasis after active infection." (PMID 33805458, 2021). "Further analysis demonstrated that the inhibition of histone H2A nuclear/cytoplasmic trafficking could relieve the protein degradation of TBK1 and IRF3, and blocked the negative regulation of histone H2A on the SVCV infection." (PMID 34868031, 2021). "During the course of infection, single‐ or double‐stranded infectious RNAs from virus accumulated inside cells are recognized by PRRs, which recruit the kinase TANK‐binding kinase 1 (TBK1) and active IRF3 by phosphorylating its C‐terminal region." (PMID 34464509, 2021). "This indicates that over-expression of TRIM26 leads to substantial reduction in IFR3, while in normal cells modest baseline IRF3 activity is seen in the absence of infection." (PMID 33419081, 2021). "The congruence of the lack of upregulation of ISGs and the decrease in IFN levels upon infection clearly indicates that TAOK2 is involved in the IFN production pathway and points towards the involvement of TAOK2 in IRF3-dependent cytokine expression (IFN-β and IP-10)." (PMID 34853303, 2021). "A transient upregulation of phosphorylated IRF3 and pIRF7, critical markers of the RIG-I/interferon signaling axis, was detected at 5 dpi for JEV and 2 dpi for CHPV that eventually declined at later days of infection." (PMID 34781742, 2021). "HAV failed to establish infection in Irf3S1/S1 mice, indicating that eliminating the transcriptional activity of IRF3 does not by itself render mice permissive for the virus." (PMID 34591933, 2021). "Of the IRFs, the mRNAs of IRF3 and IRF7 were significantly induced at 6 h post infection (PI)." (PMID 34389779, 2021). "With similar protein levels of RV VP6, indicating comparable replication between rD6/2-2g and rD6/2-2g-NSP1-null, the protein levels of IRF3 were undetectable in rD6/2-2g-infected MA104 cells whereas IRF3 was not degraded by rD6/2-2g-NSP1-null infection." (PMID 34903043, 2021). "In order to explore whether CARMA3 regulates S. aureus-induced activation of the STING/TBK1/IRF3 pathway, we first sought to determine the mRNA and protein levels of CARMA3 following the infection." (PMID 33806598, 2021). "At a molecular level, BTV has been shown to activate the transcription factors NF-κB, IRF3, and IRF7 early in the infection in HeLa cells confirming that BTV infections have the potential to trigger pro-inflammatory responses mediated by NF-κB and IFN responses mediated by IRF3/7." (PMID 34168637, 2021). "Infection by the γ134.5 null virus, but not wild type virus, also readily triggered IRF3 phosphorylation in human lung fibroblasts." (PMID 33770145, 2021). "Contrary to SARS‐CoV‐2 infection, infection of IRF3 KO T84 cells by astrovirus did not impair IFN‐mediated signaling as a similar upregulation of ISG15 was observed in both mock‐infected and astrovirus‐infected cells upon IFN treatment." (PMID 33904651, 2021). "If one considers that most of evolution is driven by lucky side-effects, the additional targets IRF3, TAB1 and NLRP12 could give a selective advantage if their cleavage would either enhance transmission or delay the response to infection." (PMID 33372854, 2021). "In particular, TLR3 might act via IRF3, producing interleukin (IL)-1α, IL-1β, IL-4, IL-6, and IFN-α and IFN-β, during the first 24 h post-infection." (PMID 34576716, 2021). "However, an attenuated MVA strain showed the opposite result, and IRF3 was activated by cGAS and STING after infection." (PMID 32983084, 2020).
infection (continued). "Notably, the extent of DNA-induced activation observed for STING, TBK1, and IRF3 during ECTVΔvSlfn and ECTV-vSlfnΔp26 infection was similar to that found in mock-infected cells, indicating that vSlfn is a critical inhibitor of cytosolic DNA sensing in ECTV." (PMID 32948585, 2020). "Further characterization revealed that Irf3−/− mice, but not Irf7−/− mice, showed a similar early increase in liver parasite burden as Ifnar1−/− mice following P. yoelii (Py17XNL) infection." (PMID 33408718, 2020). "Consistent with the microarray, protein levels of GBP2 and GBP5 were reduced in the Ifnar1−/−, Irf9−/−, Irf1−/−, Trif−/−, and Irf3−/−Irf7−/− macrophages that undergo extensive cell-cell fusion during infection but not in Myd88−/−." (PMID 32150572, 2020). "For IRF3, in the cytoplasmic RNA fraction, there was a constitutive and significant upregulation following SAV-2 infection whilst in total RNA, expression was upregulated at 18 h post infection (p < 0.0001)." (PMID 32922394, 2020). "Moreover, PPP6C depletion also enhanced KSHV primary infection-induced IFN-β mRNA induction and phosphorylation of TBK1 and IRF3 in EA.hy926 cells compared to those in control cells." (PMID 32753499, 2020). "However, infection of E. fuscus kidney cells with MERS-CoV induces the expression of IFNβ and OAS1 transcripts in an IRF3-dependent manner." (PMID 32117225, 2020). "This unique promoter feature also permits IRF3-independent basal expression of low amounts of IFNβ in the absence of infection, which can have significant impact on mounting successful innate immune responses against a variety of infections." (PMID 33408718, 2020). "In agreement with our previous observations, ECTVΔvSlfn or ECTV-vSlfnΔp26 infection triggered high levels of IRF3 phosphorylation and these were abolished in the absence of cGAS and STING, but not MAVS." (PMID 32948585, 2020). "In contrast, robust phosphorylation of IRF3 was not evident at any time point post-infection with HPV, indicating that the cGAS/STING pathway was not able to sense and respond to encapsidated vDNA." (PMID 33253291, 2020). "Conversely, ECTVΔvSlfn and ECTV-vSlfnΔp26 were completely impaired for such inhibition because infection with both mutant viruses showed notably high levels of STING, TBK1, and IRF3 phosphorylation and STING dimerization, indicative of activation of the cGAS-STING axis." (PMID 32948585, 2020). "BHK cells and Irf3−/−Irf7−/− MEF cells (both IFN-incompetent) were sensitive to the challenge infection, indicating that soluble factors do not account for SIE." (PMID 33180795, 2020). "In our study, the data of western blot proved that infection of influenza virus could increase the expression of the innate immune system-related factors TLR3, TAK1, TBK1, IRF3, and IFN-β in Raw264.7 cells." (PMID 31975996, 2019). "Most importantly, in the case of most cells pretreated with scriptaid, P/V-CPI- infection did not produce intense IRF-3 nuclear staining, but rather the staining was seen in a pattern resembling mock infected samples." (PMID 31083335, 2019). "Interestingly, in macrophages, the expression of total IRF3 or STAT2 protein levels seemed to be reduced at 2 and 6 h after infection with both types of viruses." (PMID 31673117, 2019). "These nPro/HFs and V/HFs were recently utilized, alongside IRF3 KO CRISPR/Cas9 HFs, to demonstrate that expression of viperin, ISG15, IFIT1, IFIT2, IFIT3, Mx1, and Mx2 mRNA during infection with HCMV can be induced in an IRF3-dependent, STAT1-independent manner." (PMID 31921100, 2019). "After infection, H1N1 virus mRNA was recognized by RIG-I/MAVS/IRF3 pathway and induced type I IFNs secretion, which could suppress viral replication, boost adaptive immunity, and limit acute lung injury." (PMID 30792656, 2019). "We show that SFK inhibition blocks infection in the absence of functional interferon signaling in cells lacking IRF3 or STAT1." (PMID 30917980, 2019).